CD4 (CD4 molecule)
Diseases named in the same sentence as CD4 in open-access papers (continued):
Sharing a sentence is not in itself a finding about the gene and the disease.
colitis (continued). "Consistent with a contribution of CD4+ T cells in the induction of colitis, secondary infection led to a significant increase of CD4+ T cells in the colonic lamina propria following DSS administration in combination with repeated MAP exposure." (PMID 28361039, 2017). "Our findings identify a novel mechanism of CS-induced colitis: the mediation of immune activation via T-bet/IFN-γ-mediated CD4+ T cells." (PMID 29163466, 2017). "In line with the previous findings suggesting the negative regulation of SHP2 in acute inflammation, our present study show the deletion of SHP2 in CD4+ T cells aggravates the DSS-induced colitis." (PMID 27935860, 2017). "The AT of WT cells shortened colon length and increased IFN-γ and TNF-α expression; however, the AT of IFN-γ-deficient cells did not cause those changes, indicating that IFN-γ producing CS-exposed CD4+ T cells play a substantial role in inducing colitis." (PMID 29163466, 2017). "Simultaneously, MMDP treatment markedly increased the percentage of CD4+ Foxp3+ (Treg cells) when compared with untreated TNBS-induced colitis group." (PMID 28946886, 2017). "In this study, we showed that oral administration of Hsp65-LL prevented colitis development in mice and induced CD4+Foxp3+/CD4+LAP+ Tregs in a TLR2/IL-10-dependent fashion." (PMID 28194152, 2017). "To confirm the role of CD4+ T cells in the MAP-mediated exacerbation of the DSS-induced colitis, we next treated RAG2−/− mice, which lack T and B cells with DSS and subsequently challenged them with MAP." (PMID 28361039, 2017). "We validated the role of the Th1 response in CS exposure-induced colitis using specific CD4+/8+ T-cell depletion or IFN-γ/T-bet knock-out mice." (PMID 29163466, 2017). "Adoptive transfer of naïve CD4+ T cells resulted in significantly reduced colitis following adoptive transfer." (PMID 29138469, 2017). "To confirm the role of IFN-γ in the induction of colitis via CS-stimulated CD4+ T cells, we performed an AT of lung draining lymph node CD4+CD25− T cells from WT or IFN-γ−/− mice to colitis-prone IL-10−/− mice." (PMID 29163466, 2017). "To identify specific T-cell subsets involved in CS exposure-induced colitis, we depleted CD4+ T cells or CD8+ T cells prior to CS exposure." (PMID 29163466, 2017). "The implication of CD4+NKG2D+ T cells in gut inflammation has been further shown in a murine model of transfer-induced colitis." (PMID 28926962, 2017). "While the CD4+CD45RO+hi transfer colitis model showed a gene expression profile concordant with inhibition of IL10RA, treatment with anti-miR-142-5p was concordant with induction of IL10RA and reduction in colitis." (PMID 29059189, 2017). "Here, a significant reduction of IL-10 production by Bcl-3TOE CD4+ T cells was found, probably contributing to the observed colitis phenotype in Bcl-3TOE mice." (PMID 28452361, 2017). "As the expression of the anti-inflammatory cytokine IL-10 is known to have an ameliorating effect on colitis, we also investigated the production of this cytokine by CD4+ T cells." (PMID 28452361, 2017). "To further explore possible CD9-mediated immune mechanisms in IBD, we used an alternative model of colitis induced by intraperitoneal transfer into Rag1−/− mice of CD4+CD62L+CD25−CD45RBhi naive T cells sorted from WT or CD9−/− mice." (PMID 29312336, 2017). "In conclusion, relatively high‐dose wogonin treatment (100 mg/kg) promoted the onset and severity of DSS‐induced colitis by stimulating the effector CD4+ and CD8+ cells and reducing the induction of regulatory T cells." (PMID 27641629, 2017). "The overall pathology score was significantly lower in Rag1−/− mice receiving Ccdc88bmut vs. WT CD4+ T cells, demonstrating less severe colitis in the former group." (PMID 29030607, 2017). "Ifnar1−/−-recipient mice developed severe colitis, compared with Ifnar1+/+ mice, when inoculated with CD4+ T cells from a WT mouse." (PMID 28428788, 2017).
colitis (continued). "This implies that the rehabilitating effect of MMDP in colitis is achieved by restoration of the balance between CD4+ T cell subsets." (PMID 28946886, 2017). "S. japonicum ova pre-treatment contributes to the relief of colitis and decreases mortality in a TNBS-induced colitis model, modulating the activity of CD4+CD25+Treg cells." (PMID 29163443, 2017). "Previous studies indicated that unusual CD4+ T cell populations (CD4+ TCRβdim T cell) are responsible for the development of colitis in this strain of mice." (PMID 27500935, 2016). "Isolated colon CD8+ T cells during DSS-induced colitis were added to the culture for activation of the OT-II CD4+ T cells." (PMID 26908454, 2016). "Assessment of cytokine levels in culture supernatants of MLN-derived cells demonstrated that CCR5+ CD4+ cells displayed a profile consistent with Th17 polarization during TNBS colitis." (PMID 27492684, 2016). "To test this we transferred naive WT, Ndfip2−/−, Ndfip1 cKO and cDKO CD4+ T cells into Rag1−/− recipients to induce colitis." (PMID 27088444, 2016). "In these IBD animal models, transfer of naïve (CD4+ CD45RBhi) T cells into congenic immunodeficiency mice (T cell transfer colitis model), which is known as a good CD model, is one of the most common models." (PMID 27762297, 2016). "About 5 weeks after transfer, WT naïve CD4 cells were able to induce colitis in Rag 1−/− mice, as indicated by a decrease in their body weight as compared with Rag 1−/− mice that did not receive any transferred cells (p = 0.02)." (PMID 27601345, 2016). "Later on, several other groups confirmed the antigen-specific suppressive potential of CD4+IL-10+ T cells in vivo using colitis, experimental autoimmune encephalomyelitis (EAE), collagen-induced arthritis, and allergy disease models." (PMID 27683580, 2016). "Following adoptive transfer of naïve CD4+CD45RBhi T cells, Rag2-/- mice typically develop mild to moderate colitis within 6–8 weeks." (PMID 27050757, 2016). "In the mouse-TNBS colitis model, oral administration of Imm124E increased serum levels of the anti-inflammatory cytokine IL-10 and promoted both CD4+CD25+ and CD4+Foxp3+ Tregs." (PMID 26900473, 2016). "To further assess the effects of 5-FU on TH17 cell development in vivo, we performed adoptive T cell transfer colitis experiments using CD4+CD45Rbhi cells from C57BL/6 mice to induce colitis in Rag1−/− mice." (PMID 27027355, 2016). "The rSjcystatin application after colitis decreased the proportion of Th1 subsets in these organs, due to the data of the percentage of CD4+IFNγ+ and relative expression of IFNγ mRNA descended in the spleen and MLN." (PMID 26728323, 2016). "In this study, we therefore examined the role of both TNFR1 and TNFR2 expressed by CD4 Teffs in the induction of colitis in lymphopenic Rag 1−/− mice." (PMID 27601345, 2016). "In fact, colonic CD4+ iELs of Il10−/− mice secrete elevated levels of IL-17A during colitis, which is enhanced by IL-23." (PMID 27027442, 2016). "One marked feature of the colitis induction by adoptive T-cell transfer is the high purity of inoculated cells, which often exceeds 95% of conventional CD4+CD25−CD45RBhigh cells." (PMID 27353032, 2016). "We found that CD25+ and CD25− Foxp3+CD4+ Tregs showed similar tendency as Foxp3+CD4+ Tregs during both, steady state and colitis conditions." (PMID 26908454, 2016). "In experimental colitis, macrophages and CD4+ T cells of the lamina propria produce an increased amount of IL-6." (PMID 27293323, 2016). "The co-transfer of Treg-of-B cells with CD4+CD45RBhi effector T cells into SCID mice effectively inhibited the symptoms of colitis and reduced the production of Th1 and Th17 cytokines in the MLNs and colons." (PMID 27581189, 2016). "Compared to chemically inducible models of colitis such as those based upon DSS and TNBS, AdTr of CD4+CD25− T cells into immune deficient mice more closely reflects the altered gene expression in human IBD." (PMID 26880890, 2016).
colitis (continued). "We monitored development of colitis after transfer of total CD4+ T cells in IL-15koIL-6koRAG2ko mice compared with RAG2ko, IL-6koRAG2ko and IL-15koRAG2ko recipients." (PMID 26964669, 2016). "Taken together, our data presented in this study clearly indicate that TNFR2 expressed by CD4 T cells has a deleterious effect in mouse colitis induced by transfer of naive CD4 T cells." (PMID 27601345, 2016). "Using different doses of this inoculum, which contains physiological levels of all non-T cell splenic populations but Treg cells, we showed that the augmentation of potentially colitogenic CD4+CD25− cells inoculated leads to suppression of colitis." (PMID 27353032, 2016). "In contrast, mice that were given Treg-of-B cells had mild colitis features, and mice treated with CD4+CD45RBlo cells had sporadic colitis features." (PMID 27581189, 2016). "Inflammatory phagocytes are required to infiltrate the lamina propria of the colon to establish persisting colitis after transfer of CD45RBhi CD4+ T-cell into Rag1−/− mice." (PMID 26834746, 2016). "Colitis symptoms were also presented in mice given colitogenic T cells alone, but not in mice that were also co-injected with Treg-of-B cells or CD4+CD45RBlo cells." (PMID 27581189, 2016). "Here the authors show that IL-15 promotes Foxp3 and inhibits RORγt expression in CD4 T cells, and that IL-15 is critical to suppress colitis by maintaining the Treg to Th1/Th17 ratio in a mouse model." (PMID 26964669, 2016). "Adoptive transfer of Treg-of-B cells protected mice from CD4+CD45RBhi T-cell-induced colitis, including infiltration of leukocytes, depletion of goblet cells, epithelial hyperplasia, and inhibition of Th1 and Th17 cytokines." (PMID 27581189, 2016). "These CD8+ T cells inhibited the activation and differentiation of inflammatory CD4+ T cells via IL-10 expression in the colitis model." (PMID 26908454, 2016). "The effector CD4+ T cells in C57BL/6 mice with DSS-induced colitis have long been considered as a Th1-type colitis animal model resembling CD41." (PMID 27545302, 2016). "Antibodies to Cbir1, one of the commensal-derived flagellins, were also detected in Mdr1−/− and Il-10−/− mice and in CD patients, while Cbir1-specific CD4+ T cells induced severe colitis when adoptively transferred into naive SCID mice." (PMID 26583115, 2015). "As mentioned, the development of CD4+ T cell-induced colitis in Gimap5sph/sph can be prevented by antibiotic-treatment, again confirming the critical role of the microbiota in T cell activation." (PMID 25944983, 2015). "The role of FoxP3+ Treg cells preventing colitis mediated by Th1 and Th17 cells was also proven in an experimental model with the transfer of naive CD4 +T cells to SCID mice." (PMID 25853847, 2015). "In contrast to the generally beneficial effects of vitamin, in a hybrid IL10−/−/CD4+transfer/piroxicam model of colitis, vitamin D supplementation exacerbated bone mineral density degradation induced by colitis." (PMID 27417758, 2015). "The fact that the elevated inflammatory cytokine expression such as IFNγ and IL-17A in the colon and accumulation of CD4+ T cells in cLP were observed in LTAC mice raised the question of whether these T cells turned out to gain pathogenic characters that would contribute to onset of colitis." (PMID 26132627, 2015). "Colitis was induced via adoptive transfer of CD4+ Teff cells isolated from CBir1 Tg mice into TCRβδ-/- mice." (PMID 26230654, 2015). "Splenic TCRγδ+LAP+ cells appear to play an important role in inducing CD4+Foxp3+ cells and controlling colitis because, although there is a lower frequency of TCRγδ+LAP+ cells in the spleen, the absolute number of TCRγδ+LAP+ cells is 5-fold more than in SI-LP." (PMID 26644347, 2015). "It is possible that analysis of CD4+Foxp3+ cells at earlier stages in the DSS-induced colitis model would show Treg cell expansion induced by TCRγδ+LAP+ cell treatment in the colonic lamina propria." (PMID 26644347, 2015).
colitis (continued). "Here, we discuss how defects in Gimap5 function impair immunological tolerance and lymphocyte survival and ultimately drive the development of CD4+ T cell-mediated early-onset colitis." (PMID 25944983, 2015). "They demonstrated that CD103 expression was obligatory for both populations to be immunosuppressive in vitro and to potently prevent CD4+ T cell-mediated colitis in Rag2−/− mice." (PMID 26583115, 2015). "Upregulation of Mk expression was also detected in the rat large intestine during DSS-induced colitis and was shown to activate CD4+ T cells leading to enhanced mucosal restitution during the repair process of colitis." (PMID 25944986, 2015). "Colitis was induced by adoptive transfer of CD4+ T lymphocytes isolated from either WT CBir1Tg or CCR9-/- CBir1 Tg mice into T cell-deficient TCRβδ-/- mice." (PMID 26230654, 2015). "Using a well-described T cell-dependent model of colitis, transfer of C57Bl/6 CD4+CD45RBhi T cells into C57Bl/6-Rag1−/− hosts led to intestinal inflammation 8 weeks later (no Treg)." (PMID 25998054, 2015). "Purified WT CBir1 TCR transgenic CD4+ Teff cells (1 x 106) were adoptively transferred to TCRβδ-/- recipients to induce colitis." (PMID 26230654, 2015). "The CTX treatment in TNBS-mice also induced a secretion of TGF-β, IL-10, PGE2 and LXA4 accompanied by CD4+FoxP3+ cells, suggesting their participation in the improvement of the colitis induced by TNBS." (PMID 25853847, 2015). "For example, transfer of OVA-specific CD4+ T cells from RAG-2−/− OT-II transgenic mice into RAG-2−/− recipients developed colitis only when recipient mice were colonized with OVA-expressing Escherichia coli, not with control Escherichia coli." (PMID 25944983, 2015). "Colitis induced by transferring CD4+CD25RBhigh T cells into RAG−/− mice can be prevented by CD4+CD25+ Treg cells." (PMID 25889203, 2015). "Another study suggested that RELM-β promotes the chronicity of T. muris infections as well as the severity of colitis by increasing IFNγ production by CD4+ T cells." (PMID 26285214, 2015). "The induction of T cell apoptosis by the expanded cells is another mechanism that helps them to protect against colitis induced by CD4+ CD25− T cells better than conventional DCs." (PMID 26024301, 2015). "GM-CSF, which can act in synergy with IL-5 to stimulate eosinopoiesis, was also increased in the inflamed colon compared to controls and ∼40% of CD4+ T cells were GM-CSF+ in colitis." (PMID 26200014, 2015). "The effect of CD4+CD25+CD45RBlo Treg on colitis was then studied by co-administering these cells with the T effectors." (PMID 26241231, 2015). "We have previously shown that adoptive transfer of CBir Tg CD4+ T cells induces colitis in RAG-/- or TCRβδ-/- mice via in vivo generation of Th1 and Th17 Teff cells." (PMID 26230654, 2015). "The essential role of CD4+ T cells has been demonstrated in several animal models of experimental colitis, most notably in the adoptive naïve T cell transfer into a lymphopenic host." (PMID 26583115, 2015). "Inflammatory E-cadherin + BM-DCs isolated from the CD4 + CD45RBhigh T cell colitis model promote the Th17 response, whereas the Th1 response is not significantly altered from that in response to E-cadherin- BM-DCs." (PMID 25651850, 2015). "During colitis, Lb CNRZ327 modulated the production of TGF-β, IL-6, and IL-12 in colonic tissue and of TGF-β and IL-6 in the spleen, and caused an expansion of CD4+Foxp3+ regulatory T cells in the cecal lymph nodes." (PMID 24465791, 2014). "Transfer of CD4+ CD45RBhigh T cells into severe combined immunodeficiency mice also results in colitis." (PMID 25478789, 2014). "Thus, recipients of β2i/MECL-1&β5i/LMP7-deficient T-cells develop colitis six weeks after T-cell transfer, with even higher histological scores and higher quantities of IL17α in the spleens than detected in recipients of wt CD4+ T-cells, despite enhanced numbers and frequencies of iTregs." (PMID 24740379, 2014).
colitis (continued). "Colitis mediated by CD4+ CD45RBhigh T cells is characterized by increased Th1 cytokines and Treg cell–depleted CD4+ CD45RBlow cells are characterized by an increase in Th17 cytokines." (PMID 25133396, 2014). "The rapidly proliferating naïve donor VDR KO CD8+ T cells found residence in the MLN first and then in the IEL of the Rag KO mice where they out-competed the CD4+ T cells and contributed to colitis development by inducing IL-17A and IFN-γ production." (PMID 24502291, 2014). "Colitis in HLA-B17 transgenic rats is induced by activation of INF-γ-producing CD4+ T cells whereas the chemically induced colitis in the DSS model is characterized by a Th1/Th2 response." (PMID 25369019, 2014). "IL-10 appears to have an important role in the pathogenesis of the disease in this model as SCID mice administered both CD4+CD45RBHi and regulatory T cells together with anti-IL-10 receptor antibodies develop colitis." (PMID 24616886, 2014). "During the course of spontaneously colitis in IL-2Rα−/− mice, the ratio of effector/memory CD4+ T cells significantly increased." (PMID 25133396, 2014). "The next day, the same Rag KO mice were injected with sorted 4 × 105 WT naïve CD45.1+/CD4 T cells to induce colitis." (PMID 24502291, 2014). "In that study, colitis induction by CD4+ CD45RBhi naïve T cells and the preventive effect of CD4+ CD45RBlow cells were examined using T cells derived from wild-type and A2AR-deficient mice." (PMID 25071765, 2014). "Multiple cell types participate in the pathogenesis of DSS-induced colitis including gut epithelial cells, CD4+ and CD8+ T lymphocytes, regulatory T cells, neutrophils and macrophages, resembling the pathogenic events in human colitis." (PMID 24616886, 2014). "TU-100 has been shown to decrease intestinal inflammation in models of experimental colitis, including the trinitrobenzene sulfonic acid-induced colitis in the mouse and the adoptive transfer model of CD4+ CD45RBhigh cells in the SCID knockout mouse." (PMID 24857966, 2014). "As our acute DSS model of colitis is T-cell independent, the effect of reduced CD4+ T chemotaxis to the inflamed colon would be minimal, though a significant role is likely to be attributed in a chronic setting of inflammation." (PMID 24992040, 2014). "Transfer of naïve CD4+ T cells or innate immune activation in leukopenic mice have been reported to induce colitis, whereas co-transfer of CD4+CD25+CD45RBlow T cells can prevent disease induction." (PMID 25110521, 2014). "VDR KO CD4+ T cells express more IL-17, and IFN-γ, proliferate more rapidly in a mixed lymphocyte reaction and induce more severe colitis than WT CD4 cells." (PMID 24502291, 2014). "The effect of CD8+ T cells on CD4/CD45RBhigh (naïve CD4+) T cell induced colitis in Rag KO recipients was examined." (PMID 24502291, 2014). "It is known from animal models of colitis that regulatory CD4+ T-cells can both prevent and ameliorate inflammatory colitis." (PMID 24497828, 2014). "Meanwhile, Rag1−/− hosts transferred with IL-17A−/− CD4+ CD45RBhigh T cells show more severe colitis compared to Rag1−/− mice received corresponding wild type CD4+ T cells, accompanying by increased IFN-γ level in colon." (PMID 25133396, 2014). "Collectively, these findings suggest that IFN-γ-mediated MHCII expression by IECs plays an anti-inflammatory role by reducing the accumulation of colitogenic CD4+ T cells during chronic bacterial-driven colitis." (PMID 24489792, 2014). "As expected, RAG-1−/− mice transferred with wt CD4+ T-cells developed colitis and so did transferred RAG1−/−β2i/MECL-1−/−β5i/LMP7−/− mice, with similar severity as RAG1−/−mice." (PMID 24740379, 2014). "The CD3e+CD4+CD25+FOXP3+ Tregs were significantly induced in the MLN cells from the mice with DSS-induced colitis followed with T. spiralis AES treatment compared to the DSS-induced mice (P<0.05)." (PMID 24788117, 2014).